CD34 (CD34 molecule)
Diseases named in the same sentence as CD34 in open-access papers (continued):
Sharing a sentence is not in itself a finding about the gene and the disease.
diabetes (continued). "The results revealed that as diabetes progressed, a significant negative correlation was observed between changes in the CD34-positive localization region and INS-positive localization region in the islet structure (r = −0.9092, p < 0.0001)." (PMID 36467676, 2022). "In this regard, the levels of miR-92a were shown to be reduced in CD34+ cells from individuals with diabetic retinopathy compared with control subjects and patients with diabetes without diabetic retinopathy." (PMID 32752917, 2020). "Having shown that diabetes-induced nociceptive dysfunction contributes to depressed HSPC release in ischaemia, we next investigated the relation between pain, circulating levels of SP and CD34+ HSPC mobilisation following direct stimulation of BM with G-CSF." (PMID 26358583, 2015). "Subsets of patients with diabetes with or without angiopathy were found to have significantly higher numbers of what was termed pre-EPCs (CD34+/CD133+/CD117+)." (PMID 24782825, 2014). "In contrast to the total CD34+ cell population, in non-diabetic patients with MVD (PAD or CAD), the CD34+KDR+ progenitor cell subset was reduced to the same extent (1.7-fold reduction) as observed in diabetes when compared with healthy controls (p < 0.05)." (PMID 22648662, 2012). "Similarly a 2.5-fold increase was seen for CD133+CD34+ cells in the NGT group (p = 0.019) at 2 hours following 75 g glucose load, which was blocked in pre-diabetes group (p = 0.024)." (PMID 21219665, 2011). "Furthermore when the pre-diabetes group was further split into IFG and IGT, the glucose mediated increase in CD34+ and CD133+CD34+ was significantly blocked for the IGT subjects." (PMID 21219665, 2011). "Our PAD patients with diabetes had a borderline significant decrease in the number of CD34+ cells in peripheral blood; the lack of significance could be due to the small number of study participants." (PMID 37895025, 2023). "This is related to larger individual variations in cell mobilization/expansion capacity, due to the frequent co-morbidities presented by many of these patients (diabetes mellitus, smoking, elderly patients, etc.), which are known to have negative impacts on CD34+ mobilization by G-CSF." (PMID 35420389, 2022). "In addition, a previous study reported that the duration of diabetes, and not the magnitude of hyperglycemia (HbA1c), contributed to CD34+ cell number." (PMID 36140236, 2022). "The diabetes models showed that CD34 has the potential to be used as a biomarker for monitoring β-cell failure in the progression of diabetes, i.e., a strong linear and negative correlation exists between the loss of β-cells and increase of CD34 cells during disease progression." (PMID 36467676, 2022). "In patients with T1D, the levels of hematopoietic stem/progenitor cells (CD34+ CD133+, CD34+ CD45dim) were reduced and correlated positively with CV and time in hypoglycemia estimated by flash glucose monitoring; the relationships were mitigated in long-lasting diabetes." (PMID 34360550, 2021). "However, when split into the type 1 diabetes (n = 30) and non-diabetes control (n = 30) groups, the relationships were no longer significant, except for HbA1c and CD34+CD45dimVEGFR2+CXCR7+ EPCs (r = − 0.364, p = 0.048) in the type 1 diabetes group." (PMID 34267242, 2021). "From the negative binomial regression results, diabetes was the only health condition to affect EPC numbers (cells which were negative for CD45 and positive for CD34, CD133 and KDR)." (PMID 39186241, 2024). "Using established FACS protocols for the detection of EPCs and SMPCs we observed that the frequency of circulating CD34+ and CD34+KDR+ cells is reduced in patients with diabetes, whereas the levels of CD14+CD105+ SMPCs are not significantly changed by the presence of diabetes." (PMID 22648662, 2012).
diabetes (continued). "The proportion of CD34+/CXCR4+ cells within blood mononuclear cells was 1.96 times higher after STEMI compared with NSTEMI (GMR = 1.96, 95% CI 0.87, 4.37) and 1.55 times higher in patients with diabetes compared to patients without diabetes (GMR = 1.55, 95% CI 0.77, 3.13)." (PMID 36465463, 2022).
angiosarcoma (84 papers, 2005 to 2026). A malignant tumor arising from the endothelial cells of the blood vessels. "Histopathologic confirmation remained the gold standard, with strong positivity for CD31, ERG and CD34 supporting the diagnosis of angiosarcoma." (PMID 40900681, 2025). "Other tumors that can be excluded and histologically matched tumor types are angiomyolipoma (melan A, S100 protein), gastrointestinal stromal tumor (DOG-1), epithelioid hemangioendothelioma (CD34), and angiosarcoma (CD34)." (PMID 40336612, 2025). "Among malignant tumors, angiosarcomas exhibit aggressive hematogenous dissemination linked to their vascular nature and endothelial marker expression (CD31, CD34, ERG)." (PMID 40427120, 2025). "Vascular endothelial markers such as CD31 and CD34 and epithelial markers such as cytokeratin are useful in differentiating angiosarcoma." (PMID 39463621, 2024). "CD31 seems to be a more sensitive and specific immunoantibody than CD34 in case of poorly differentiated angiosarcoma." (PMID 39845895, 2024). "Angiosarcoma shows higher CD34 expression than SMARCA4-UT, expresses diffuse CD31 positivity, and typically exhibits endothelial multilayering." (PMID 38542211, 2024). "Immunohistochemical profiling is essential for differentiating PASH from low-grade angiosarcoma, with specific markers such as CD34, vimentin, desmin, actin, and progesterone receptor aiding in the correct diagnosis and preventing misinterpretation." (PMID 39564024, 2024). "angiosarcoma has characteristic expression of endothelial markers CD31, CD34, factor VIII associated antigens and vascular endothelial growth factor." (PMID 37717004, 2023). "CD31 is expressed in more than 90% of angiosarcomas, and the positive rate of CD34 in angiosarcomas is 50–60%." (PMID 33509230, 2021). "The immunohistochemical staining indicated CD31 (+) and CD34 (+) confirming a diagnosis of metastatic angiosarcoma." (PMID 34026609, 2021). "Positive immunohistochemical staining for CD31 and CD34, favoring angiosarcoma, was observed in all patients." (PMID 33827427, 2021). "Other differentials included epithelioid gastrointestinal stromal tumor (GIST), solitary fibrous tumor (SFT), and angiosarcoma due to positive staining for CD34." (PMID 34797454, 2021). "Angiosarcomas are positive for vascular markers, including cluster of differentiation (CD) 31 and CD34." (PMID 33355800, 2021). "Both hemangioma and angiosarcoma express CD31 and CD34, and angiosarcoma also expresses cytokeratin, making the diagnosis of these tumors potentially challenging." (PMID 29996478, 2018). "It is also important to note that positive stainings for CD31, CD34, and vimentin are also found in epithelioid angiosarcoma of bone and soft tissue." (PMID 28865487, 2017). "A bimodal expression pattern for CD34 was noted in all of the canine hemangiosarcoma cell populations." (PMID 25295160, 2014). "The cells stain for vascular markers such as CD 31 (90% angiosarcomas), CD34 (50% of angiosarcoma), and less often with von Willebrand factor and occasionally show cytokeratin immunoreactivity." (PMID 23198186, 2012). "Other entities, such as angiosarcoma and gastrointestinal stromal tumour, also express CD34 and vimentin epitopes." (PMID 17118185, 2006). "CD31 and CD34 are expressed in more than 90% and 50-60% of angiosarcomas respectively." (PMID 39845895, 2024). "Kaposi's sarcoma must also be differentiated from angiosarcoma due to its similar histological features and IHC staining patterns; however, the patient population is typically associated with HIV and has immunopositivity for CD-117 (KIT) and CD-34 markers." (PMID 37113364, 2023). "In addition, CD31 immunohistochemistry was identified to be valuable in the differential diagnosis; however, a variety of markers are required for the diagnosis of angiosarcoma, such as CD34, FVIII, vimentin and pan-CK." (PMID 25289092, 2014). "However, CD31 and CD34 stain positive in both angiosarcoma and reactive angioendotheliomatosis." (PMID 40255814, 2025).
angiosarcoma (continued). "Furthermore, a literature review found that angiosarcomas may also test positive for CD-117 and CD-34, which should prompt additional testing to stratify the disease." (PMID 37113364, 2023). "Angiosarcomas usually express vascular and endothelial markers, including ERG, CD31, CD34, and factor VIII, with CD31 being the most sensitive." (PMID 39958141, 2025). "Spindle cells in angiosarcoma express endothelium markers such as CD31, CD34, and the von Willebrand factor antigen." (PMID 41488269, 2025). "CD34 expression is uncommon in LGMS, whereas angiosarcoma typically demonstrates strong positivity for this endothelial marker." (PMID 40556675, 2025). "Angiosarcomas typically express endothelial markers, including factor VIII-related antigen (factor VIII), CD31, CD34, and vascular endothelial growth factor (VEGF)." (PMID 40542819, 2025). "Although EHE expresses similar molecular markers to angiosarcoma (CD31, CD34, and ERG), angiosarcoma differs greatly from EHE in terms of light microscopy morphology and often exhibits MYC amplification without CAMTA1/TFE3 expression." (PMID 40896782, 2025). "Both CHE and angiosarcoma show immunopositivity for CD31, CD34, and VEGF, but angiosarcoma tends to exhibit more diffuse staining, while CHE demonstrates a more heterogeneous staining pattern." (PMID 40283372, 2025). "Liver biopsy confirmed metastatic angiosarcoma, likely of cardiac origin, with positive immunohistochemical markers (CD31, CD34, CD117; Ki-67 40%)." (PMID 40895975, 2025). "Histologically, angiosarcoma is characterized by polygonal, rounded, spindled endothelial cells with immunochemical analysis positive for CD31, CD34, von Willebrand factor, and vascular endothelial growth factor (VEGF)." (PMID 40125238, 2025). "The endothelial markers CD31, CD34, and ERG will be positive in pyogenic granuloma, hemangioma, vascular malformation, Kaposi sarcoma, and angiosarcoma." (PMID 40895846, 2025). "In our case, the resected tissue was consistent for moderately differentiated angiosarcoma with positive immunohistochemical stains for FL1, MSA, SMA, PHH3, CD34, and CD31." (PMID 38903323, 2024). "Biopsy results showed moderately differentiated angiosarcoma, with positive immunohistochemical staining for FLI-1, muscle-specific actin (MSA), smooth muscle actin (SMA), PHH3, CD34, and CD31." (PMID 38903323, 2024). "Negative expression of common endothelial vascular markers such as ERG (n = 1), CD34 (n = 16), CD31 (n = 15), and factor VIII-related antigen (n = 10) help confirm that the tumor is epithelial in origin, which aids in ruling out angiosarcoma." (PMID 39199675, 2024). "Similar to AH, well-differentiated angiosarcoma can also express EGR, CD31, CD34, and other vascular endothelial immunohistochemical markers, and they also present with anastomosed vascular channels." (PMID 37171299, 2023). "Epithelioid angiosarcoma is expected to be strongly positively stained with CD31, CD34, panCK, and EMA during immunohistochemical examination." (PMID 34757619, 2023). "Ultrasound-guided biopsy was performed, and the patient was ultimately diagnosed with an angiosarcoma based on final positive results for both CD31 and CD34 markers." (PMID 33521065, 2021). "CD31 expression, used together with CD34 and ERG, is the gold standard for identifying endothelial differentiation in angiosarcoma." (PMID 35049205, 2021). "Further, immunohistochemical staining of CD34 and ERG, markers of vascular endothelium, distinguishes CRDD from angiosarcoma." (PMID 33354400, 2021). "In poorly differentiated angiosarcomas, the sensitivity and specificity of CD31 were more effective than that of CD34." (PMID 33509230, 2021). "Immunohistochemistry was positive for antigens related to CD31 and CD34, and C-MYC oncogene amplification, confirming the diagnosis of angiosarcoma induced by breast irradiation." (PMID 33295433, 2020).
angiosarcoma (continued). "Elsewhere, the vascular markers are essential for the diagnosis of certainty of the angiosarcoma, such as CD31, CD34, and the Factor-VIII-related antigens." (PMID 31692820, 2019). "Even though CD34 has been reported to be positively expressed with some cases of angiosarcoma and myofibrosarcoma, 90% of DFSP cases show positive reaction to CD34." (PMID 30918552, 2018). "Immunohistochemistry revealed strong antigenicity for CD31 and CD34, and weak antigenicity for D2-40 and Factor VIII indicating a diagnosis of angiosarcoma that was corroborated at both UC San Diego Health and MD Anderson." (PMID 30460329, 2018). "Although CD8 staining of the lining cells in splenic angiosarcoma has been reported, the main endothelial cell markers, including CD31, CD34, factor VIII–related antigen, and the histiocytic marker CD68, should exhibit strong positivity." (PMID 29378604, 2018). "A definitive diagnosis of angiosarcoma is generally confirmed using a combination of imaging, histology, and positive expression of vascular protein markers including CD31 and CD34." (PMID 30460329, 2018). "Differently from CD34 and CD31 immunomarkers, the CD105 immunostaining is useful in the differential diagnosis since it is overexpressed in angiosarcoma cells." (PMID 28053797, 2016). "Epithelioid angiosarcomas stain strongly positive for Vimentin and in most cases are immunoreactive for vascular markers CD31, CD34, and VEGFR-3 and Factor VIII." (PMID 26290766, 2015). "On immunohistochemical analysis, the angiosarcoma component expresses endothelial markers CD31, CD34 and, less extensively, von Willebrand factor (factor VIII)." (PMID 25487416, 2014). "Previous studies using hemangiosarcoma cell lines demonstrated expression of early hematopoietic (CD34, CD117, and CD113) and endothelial progenitor (CD34 and CD133) markers." (PMID 25295160, 2014). "While expression of CD34 and CD117 by both the CSF-1Rlow and CSF-1Rhigh cells was observed in the hemangiosarcoma cell lines, expression of CD133 was exclusive to the CSF-1Rhigh cell subpopulation." (PMID 25295160, 2014). "Endothelial (vascular) markers are necessary for warranting definitive diagnosis of angiosarcoma such as CD31, CD34, and factor VIII-related antigens." (PMID 23844302, 2013). "Immunohistochemically, the lining cells of both AVL and angiosarcoma show positivity for CD31 and variable positivity for D2-40, CD34." (PMID 23050180, 2012). "Expression of at least one of the endothelial markers including CD31, CD34, factor VIII and FLI-1, is required to confirm the diagnosis of angiosarcoma." (PMID 22208720, 2011). "The use of immunohistochemical markers for endothelium, CD31, CD34 and factor VIII, confirm most angiosarcomas including poorly differentiated ones." (PMID 22185665, 2011). "Angiosarcomas express (to a greater or lesser degree) the usual vascular antigens, including von Willebrand factor, CD31, and CD34." (PMID 20179806, 2010). "Since both angiosarcomas and carcinomas can be cytokeratin positive, it is important to perform immunohistochemistry using a large panel of markers including CD31, CD34, and Ulex Europaeus lectin." (PMID 17601346, 2007). "In this review, testicular angiosarcomas showed positive immunoreactivity to Factor VIII-related antigen, CD31, CD34, and Ulex Europaeus lectin in all the cases in which they was used." (PMID 17601346, 2007). "Angiosarcomas arise from the endothelial cells of blood vessels and stain for filament proteins vimentin, factor VIII, and CD34." (PMID 17603895, 2007). "Histologically, angiosarcoma is characterized by spindled, polygonal, epithelioid, and primitive round cells, with expression of both vascular and endothelial antigens on immunohistochemistry, including Factor-VIII, CD31, CD34, and ERG." (PMID 39958141, 2025).
angiosarcoma (continued). "Considering the current hypothesis that angiosarcomas originate from blood vessel and lymphatic endothelial cells, the expression of endothelial markers such as FLI1, ERG, CD31, and CD34 becomes pivotal." (PMID 38902365, 2025). "Although there is no pathognomonic immunohistopathological profile, angiosarcomas stain positive for at least one of the following endothelial cell markers: CD34, CD31, ERG, FLI1, and factor VIII-related antigen." (PMID 40255814, 2025). "However, angiosarcoma lacks cartilaginous differentiation and displays positivity for CD31 and CD34." (PMID 40585664, 2025). "Thus, combinations of one or more of these vascular markers [CD31, CD34, ERG, and FLI1], along with other immunomarkers are required for prompt and accurate diagnosis of angiosarcoma." (PMID 39845895, 2024). "In the pulmonary epithelioid angiosarcoma, immunopositive for CD31, CD34, and EGR." (PMID 32118771, 2020). "In addition to including various vascular endothelial markers (ECSCR, TIE1, CD34, CDH5, ESAM), the angiosarcoma gene signature also included ROS1, supporting a possible broader role of ROS1 in the pathogenesis of this disease." (PMID 23637631, 2013). "However, it is important to note that although the literature supports CD34 staining as one of the most sensitive markers for angiosarcoma, it can be negative, as it was in our case." (PMID 40295306, 2025). "In addition, the lack of synaptophysin, AE1/AE3 cytokeratin, S-100 and CD34 expression ruled out pheochromocytoma, metastatic carcinoma, malignant peripheral nerve sheath tumor, and angiosarcoma, respectively." (PMID 38110958, 2023). "Therefore, the endothelial markers, CD31 and FVIII, in addition to immunopositivity for vascular markers, CD34 and FVIII related antigen, may be added to the immunohistochemical panel when determining a diagnosis of angiosarcoma." (PMID 25289092, 2014). "As in our case, usually in angiosarcomas CD34 highlights mainly the uninvolved background vessels, and in fact, there are different reports that have shown variable reaction patterns to CD34 ranging from completely negative to approximately 80% positivity of the neoplastic cells." (PMID 22185665, 2011). "The cells of angiosarcoma are positively stained for vimentin, the endothelial cell markers such as CD31, CD34, and factor, and negatively for epithelial marker such as cytokeratin and EMA, however, in the epithelioid angiosarcoma, it may be stained as positive." (PMID 16159405, 2005). "Similarly, a negative CD31 and CD34 exclude angiosarcoma, which typically expresses these markers." (PMID 40718269, 2025). "After further processing, an additional pathological report revealed an epithelioid angiosarcoma defined by massively proliferating epithelioid cells strongly positive for ERG and CD31 and negative for CD34." (PMID 38994239, 2024). "The absence of SF-1, chromogranin A/synaptophysin, AE1/AE3 cytokeratin, S-100, CD34, and HMB-45 ruled out pheochromocytoma, metastatic carcinoma, malignant peripheral nerve sheath tumor, angiosarcoma, and malignant melanoma, respectively." (PMID 38110958, 2023). "The immunohistochemical stains showed different staining patterns between angiosarcoma and undifferentiated carcinoma (angiosarcoma: cytokeratin [AE1/AE3]-negative/CD31 and CD34-positive; carcinoma: cytokeratin-positive/CD31 and CD34-negative)." (PMID 27872782, 2016). "While both lesions stain positively for CD34, CD31 is usually negative in PASH but positive in angiosarcoma." (PMID 25544925, 2014). "Reciprocal analysis of the angiosarcoma of rat case 4 in Romania showed that the tissue did not express the human proteins CD31, CD34 or D2-40." (PMID 23105973, 2012). "In contrast to an angiosarcoma, the cells of ASCC are negative for endothelial markers such as CD31, CD34 and von Willebrand factor and these markers must be included in differentiating ASCC from angiosarcoma." (PMID 21223553, 2011).